TPBG (trophoblast glycoprotein)
Diseases named in the same sentence as TPBG in open-access papers:
TPBG is named in the same sentence as 47 diseases in open-access papers, as found by Europe PMC text mining. Sharing a sentence is not in itself a finding about the gene and the disease. The quoted sentences say what the papers report.
colorectal cancer (7 papers, 2006 to 2025). A primary or metastatic malignant neoplasm that affects the colon or rectum. "5T4 (trophoblast glycoprotein) is highly expressed by trophoblast in addition to a wide range of solid tumours (e.g., renal, lung, breast, ovarian, endometrial, bladder, PDAC, oesophageal, gastric and colorectal carcinomas in addition to malignant mesothelioma)." (PMID 36831514, 2023).
lung carcinoma (5 papers, 2015 to 2025). "Recent studies have shown that TPBG/5T4 is expressed in tumor-initiating cells in lung cancer, and high expression in several cancer types has been associated with inferior clinical outcome." (PMID 26496203, 2015).
ovarian carcinoma (5 papers, 2016 to 2023). A malignant neoplasm originating from the surface ovarian epithelium. "By comparing RNA‐seq data of 88 normal ovaries in GTEx and 419 primary ovarian cancer cases in TCGA, we observed that TPBG expression was significantly upregulated in the tumor tissues (p < .001)." (PMID 34766126, 2020).
renal cell carcinoma (5 papers, 2005 to 2025). "After extracting the protein expression from the HPA database, we discovered that the levels of TPBG signals were increased in multiple cancers, including Lung AC, Lung SACC, Head and Neck SQCC, and Renal Cell Carcinoma." (PMID 39823250, 2025). "5T4 (trophoblast glycoprotein, TPBG) is a transmembrane tumor antigen expressed on more than 90% of primary renal cell carcinomas (RCC) and a wide range of human carcinomas but not on most somatic adult tissues." (PMID 31686124, 2019).
breast carcinoma (4 papers, 2020 to 2025). "The results of MTT, colony formation, and Edu assays indicated that TPBG overexpression caused a significant increase of breast cancer cell proliferation." (PMID 37495592, 2023). "We revealed a novel mechanism whereby CAF-derived exosomal circTBPL1 induced progression and metastasis of breast cancer, and confirmed the significant effect of circTBPL1/miR-653-5p/TPBG regulatory axis." (PMID 37495592, 2023). "In the present study, we found that TPBG was obviously overexpressed in breast cancer tissues, and TPBG overexpression promoted while TPBG knockdown inhibited the cell proliferative and metastatic abilities." (PMID 37495592, 2023). "Collectively, our data demonstrated that circTBPL1 derived from CAFs played a critical role in regulating tumor growth and metastasis through miR-653-5p/TPBG axis in breast cancer." (PMID 37495592, 2023). "The consistent result of TPBG protein expression was also identified in breast cancer tissues by IHC." (PMID 37495592, 2023). "Taken together, these results revealed that exosomal circTBPL1 derived from CAFs contributed to cancer progression via miR-653-5p/TPBG pathway, indicating the potential of exosomal circTBPL1 as a biomarker and novel therapeutic target for breast cancer." (PMID 37495592, 2023). "The breast cancer cells were transfected with pLCDH-ciR + si-NC, circTBPL1 + si-NC, and circTBPL1+ si-TPBG, respectively." (PMID 37495592, 2023). "The overexpression efficiency of TPBG in breast cancer cells was confirmed using qRT-PCR and western blot assays." (PMID 37495592, 2023). "All these results suggested that a circTBPL1/miR-653-5p/TPBG axis existed in breast cancer, and circTBPL1 might exerts tumor-promoting effects through regulating the miR-653-5p/TPBG axis." (PMID 37495592, 2023). "Considering the upregulated expression of TPBG in breast cancer tissues, we wonder whether TPBG could promote cancer progression." (PMID 37495592, 2023). "Moreover, western blot revealed that TPBG overexpression activated the EMT pathway in breast cancer cells." (PMID 37495592, 2023). "Hence, these observations revealed that TPBG exhibited a tumor-promoting role, and was essential for circTBPL1-mediated breast cancer progression." (PMID 37495592, 2023). "Moreover, TCGA database showed that the expression of TPBG was upregulated in various cancer tissues compared to normal tissues, including breast cancer." (PMID 37495592, 2023). "Then the hypothesis that TPBG was the target of miR-653-5p in breast cancer cells was further demonstrated using luciferase reporter assays." (PMID 37495592, 2023). "The results indicated that miR-653-5p had binding sites with TPBG, and miR-653-5p inhibited while circTBPL1 promoted the expression of TPBG in breast cancer cells, inferring that miR-653-5p might be a bridge for the regulation of TPBG by circTBPL1." (PMID 37495592, 2023). "Consistently, TPBG suppression led to attenuated cell proliferation and metastasis abilities, further supporting the tumor-promoting role of TPBG in breast cancer." (PMID 37495592, 2023). "Taken together, the present study demonstrated that CAF-derived exosomal circTBPL1 could facilitated the growth and progression of breast cancer, which was mediated by protecting TPBG from miR-653-5p-mediated degradation in the recipient cancer cells." (PMID 37495592, 2023). "According to the MTT, colony formation, and Edu assays, knockdown of TPBG could attenuate the promoting effect of circTBPL1 on breast cancer proliferation." (PMID 37495592, 2023). "Moreover, we also found that TPBG expression in breast cancer cells was upregulated by exosomes derived from CAFs, however, the expression of TPBG remained unchanged when treated by exosomes derived from CAFs transfected with si-circTBPL1." (PMID 37495592, 2023).
breast carcinoma (continued). "Besides, the exosomes from si-NC CAFs could elevated the expression level of TPBG in breast cancer cells compared with control group, NF group, and si-circTBPL1 CAF group, which correspond to the expression alteration of circTBPL1 caused by exosomes." (PMID 37495592, 2023). "Additionally, TPBG was selected as a downstream target gene, and circTBPL1 could protect TPBG from miR-653-5p-mediated degradation, leading to enhanced breast cancer progression." (PMID 37495592, 2023).
esophageal squamous cell carcinoma (4 papers, 2019 to 2025). Esophageal squamous cell carcinoma (ESCC) is a type of esophageal carcinoma (EC) that can affect any part of the esophagus, but is usually located in the upper or middle third. "CV9201 is a cancer immunotherapy based on RNActive® technology, encoding five antigens associated with NSCLC: New York esophageal squamous cell carcinoma-1 (NY-ESO-1), melanoma antigen family C1 and C2 (MAGE-C1 and MAGE-C2), survivin, and trophoblast glycoprotein (5T4)." (PMID 41007751, 2025).
gastric cancer (4 papers, 1992 to 2025). A primary or metastatic malignant neoplasm involving the stomach. "For instance, high TPBG expression has been observed in tumor tissues, including bladder, breast, ovarian, pancreatic, and gastric carcinomas, and it has been closely associated with poor clinical outcomes in colorectal, ovarian, and gastric cancers." (PMID 40136427, 2025). "Trophoblast glycoprotein (TPBG) plays a significant part in the growth of specific cancers, yet its connection to gastric cancer (GC) remains uncertain." (PMID 39823250, 2025). "Furthermore, TPBG protein levels in stomach tissues were lower compared to stomach cancer tissues." (PMID 39823250, 2025).
mesothelioma (3 papers, 2024 to 2025). A usually malignant and aggressive neoplasm of the mesothelium which is often associated with exposure to asbestos. "Lately, the trophoblast glycoprotein (5T4), an oncofetal protein with low expression in normal tissues, has been included among mesothelioma TAAs and found to be equally expressed in all histological subtypes." (PMID 40918456, 2025).
preeclampsia (3 papers, 2013 to 2023). Preeclampsia is a hypertensive disorder of pregnancy that is characterized by new-onset hypertension with proteinuria presenting after 20 weeks of gestation, and depending on mild or severe forms may initially present with severe headache, visual disturbances, and hyperreflexia. "In summary, we identified three key inflammation-associated genes, namely INHBA, OPRK1, and TPBG, which can be used as potential genetic biomarkers for preeclampsia prediction and treatment, and established a nomogram as a predictive model." (PMID 35880174, 2022). "Subsequently, we analyzed the expression of INHBA, OPRK1, and TPBG in preeclampsia placental tissue and non-preeclampsia placental tissue." (PMID 35880174, 2022). "We further analyzed INHBA, OPRK1, and TPBG, which played a crucial role in the development of preeclampsia." (PMID 35880174, 2022). "The expression of INHBA, OPRK1, and TPBG showed significant differences between preeclampsia and non-preeclampsia samples." (PMID 35880174, 2022). "The binding energy between curcumin and TPBG-4cnc, OPRK1-4djh, and RELA-3qxy was less than −7.0 kcal/mol, which further suggested the effectiveness of curcumin for the treatment of preeclampsia." (PMID 35880174, 2022). "The authors found that the INHBA gene together with the OPRK1 and TPBG genes are key inflammation-related genes that affect the course of pregnancy (the expression of INHBA and TPBG genes in complicated preeclampsia pregnancy is higher, and the OPRK1 gene is lower, compared with normal pregnancy)." (PMID 37511900, 2023). "The binding affinity for curcumin and TPBG-4cnc, OPRK1-4djh, and RELA-3qxy was less than −7.0 kcal/mol, indicating that they have strong binding energy, which further suggests the effectiveness of curcumin in the treatment of preeclampsia." (PMID 35880174, 2022).
Alzheimer disease (2 papers, 2020 to 2025). A progressive, neurodegenerative disease characterized by loss of function and death of nerve cells in several areas of the brain leading to loss of cognitive function such as memory and language. "Both TSPOAP1 and TSPOAP1-AS1 were shown to be correlated with Alzheimer’s disease (AD) progression through interactions with a risk factor gene of AD, trophoblast glycoprotein (TPBG)." (PMID 32392798, 2020). "Additionally, TPBG and CEP112 have been shown to be related to glioblastoma and Alzheimer’s disease." (PMID 41245832, 2025).
pancreatic cancer (2 papers, 2022 to 2025). "A positive TPBG expression result is associated with a poor outcome in colorectal, gastric, ovarian, NSCLC, HNSCCs, and pancreatic cancer." (PMID 39823250, 2025).
breast tumor (1 paper, 2017). "The ADCs prepared with drug-linker coupled through the cysteine-insertion after site HC-S239 of anti-5T4 (trophoblast glycoprotein, an oncofetal antigen on breast tumor) demonstrated potent dose-dependent antitumor activity in a mouse xenograft model." (PMID 29120405, 2017).
glioma (1 paper, 2021). A benign or malignant brain and spinal cord tumor that arises from glial cells (astrocytes, oligodendrocytes, ependymal cells). "In addition, there is no research on B4GALT7, CHST12, G6PC2 and TPBG in glioma." (PMID 33553434, 2021).
lung adenocarcinoma (1 paper, 2023). A carcinoma that arises from the lung and is characterized by the presence of malignant glandular epithelial cells. "Further experiments indicated that TPBG could serve as an effector of long non-coding RNAs LINC00342, inducing metastasis in lung adenocarcinoma through regulating miR-15b/TPBG axis." (PMID 37495592, 2023).
memory impairment (1 paper, 2022). "As a result, 3 DEmRNAs from CCI with memory impairment model rats (ATF3, C1QC, and CD68) and 13 DEmRNAs from SNI and CCI models (ADAMTS2, BCL6B, CLCF1, RBP1, and TPBG, among others) overlapped with SNI and CCI models, respectively." (PMID 35547819, 2022).
myocardial infarction (1 paper, 2023). Gross necrosis of the myocardium, as a result of interruption of the blood supply to the area, as in coronary thrombosis. "Of the 4 hub genes, ADM was upregulated in CAD (GSE56885), PPFIA4 and TPBG were upregulated in patients with ischemic heart disease (GSE48166), and FAM162A was downregulated in patients with myocardial infarction (GSE141512)." (PMID 37637145, 2023).
oncocytoma (1 paper, 2024). "In a study aimed at distinguishing ChRCC from RO, the genes LMBRD1, TPBG, MANEA, and HACE1 were integral components of a 30-gene signature known as chromophobe and oncocytoma-related gene signature (COGS)." (PMID 39684226, 2024).
soft tissue sarcoma (1 paper, 2021). A malignant neoplasm arising from muscle tissue, adipose tissue, blood vessels, fibrous tissue, or other supportive tissues excluding the bones. "The expression of 5T4/trophoblast glycoprotein was evaluated in several histological subtypes of soft tissue sarcoma (STS) to determine whether the prevalence and level of expression of this membrane-associated glycoprotein is sufficient for use in targeted therapies." (PMID 34638324, 2021).
tumor (49 papers, 1988 to 2025). "Previous studies have confirmed the significant association of TPBG with tumor malignancy and poor prognosis." (PMID 37495592, 2023). "TPBG was a leucine-rich transmembrane glycoprotein that encoded cell adhesion, which was expressed in many tumor tissues but hardly in normal adult tissues and was involved in the directional movement of cells." (PMID 36699465, 2022). "ABR-217620 consists of a mutated variant of the Sag See containing distinct epitopes of SEA (SEA/E-120) linked to a Fab-moiety of a monoclonal antibody recognizing the tumor-associated oncofetal trophoblast glycoprotein antigen 5T4." (PMID 24194959, 2013). "In addition, TPBG expression is to cause vascular remodelling in the tumour's microenvironment, which further accentuates tumour growth and invasion." (PMID 39823250, 2025). "EPZ004777 downregulated tumor-associated genes such as TPBG, ZNF185, and SNX19, suggesting its ability to inhibit tumor progression." (PMID 40136427, 2025). "TPBG expression has been reported to induce vascular remodeling in the tumor microenvironment, thereby playing a crucial role in tumor growth and invasion." (PMID 40136427, 2025). "In consistent with the in vitro results, exosomal circTBPL1 also promoted tumor growth in vivo by miR-653-5p/TPBG axis." (PMID 37495592, 2023). "Other onco-fetal antigens, such as trophoblast glycoprotein (TPBG) are also thought to be specific to tumours as they are present only during fetal development." (PMID 30096953, 2018). "In vitro and in vivo tumour models were utilised to evaluate the function of TPBG in GC." (PMID 39823250, 2025). "Additionally, the expression of tumor-associated genes such as CT45A3, TPBG, HOXA4, ZNF185, and SNX19 was significantly downregulated." (PMID 40136427, 2025). "Taken together, knockdown TPBG expression can suppress xenograft tumour growth, suggesting that reducing TPBG levels could be advantageous in treating GC." (PMID 39823250, 2025). "Therefore, our study primarily focused on three intriguing tumour-associated antigens (TAAs), namely, receptor tyrosine kinase-like orphan receptor 1 (ROR1), trophoblast glycoprotein (TPBG/5T4) and carbonic anhydrase IX (CAIX)." (PMID 28687750, 2017). "The TPBG mRNA from the database was compared between cancerous and adjacent samples of STAD patients, revealing an obvious increase in tumour samples (p < 0.001)." (PMID 39823250, 2025). "It was reported that TCR-T cells targeting trophoblast glycoprotein (5T4) have tumor killing effects in vitro, and greater than 90% of RCC cells express the 5T4 antigen." (PMID 35725570, 2022). "TPBG expression increased in several tumour tissues (including GC) more than in adjacent noncancerous tissues." (PMID 39823250, 2025). "Interestingly, RNA expression in tumor tissue was only evident for CEACAM1, MAGEA4, SRC, TPBG, GPA33, and SUB1, with the highest and lowest expression for SRC and MAGEA4, respectively." (PMID 39949781, 2025).
cancer (40 papers, 1994 to 2025). A tumor composed of atypical neoplastic, often pleomorphic cells that invade other tissues. "TPBG, encoding a leucine-rich transmembrane glycoprotein that may participate in cell adhesion, has been detected to be overexpressed in a wide range of human malignant tumors." (PMID 37495592, 2023). "Similar epigenetic mechanisms are known to regulate other oncofetal genes, including carcinoembryonic antigen and trophoblast glycoprotein, which are aberrantly re-expressed in cancer." (PMID 40136335, 2025). "TPBG has been identified as an oncofetal antigen that is highly expressed in various types of cancer." (PMID 40136427, 2025). "Furthermore, TPBG, a glycoprotein that inhibits the Wnt/β-catenin pathway and is associated with poor clinical outcomes in various cancer types, shows decreased expression following EPZ004777 treatment, which may contribute to the inhibition of cancer cell proliferation." (PMID 40136427, 2025). "Given TPBG's involvement in various cancers, we aimed to investigate its significance in GC as well." (PMID 39823250, 2025). "The translational production of circulating 5T4 mRNA is a trophoblast glycoprotein present in epithelial malignancies and is a potential biomarker for cancer detection." (PMID 24252206, 2013). "TPBG has been primarily studied in embryonic stem (ES) cell differentiation and cancer metastasis." (PMID 34876581, 2021). "More impressively, it was reported that TPBG was involved in the progression of human pericyte migration as well as its angiogenic ability, which might be related to the enhanced angiogenesis feature of cancer." (PMID 37495592, 2023). "Overall, these findings show the promise of EPZ004777 as a therapeutic agent, with TPBG, ZNF185, and SNX19 serving as focal points for further research to refine its application in cancer treatment." (PMID 40136427, 2025). "Additionally, TPBG modulates cell adhesion, cytoskeletal organization, and mobility by facilitating functional C-X-C chemokine receptor type 4 (CXCR4) expression, leading to C-X-C motif chemokine 12 (CXCL12)-mediated chemotaxis in differentiating ES cells, embryonic fibroblasts, and cancer cells." (PMID 34876581, 2021).
neurological disorders (1 paper, 2025). "The TPBG and CEP112 genes, which are implicated in neurological disorders, may offer insights into the onset of ALD." (PMID 41245832, 2025).
TPBG also shares sentences with these, for which no sentence is quoted: adenocarcinoma (2 papers); bladder cancer (2); glioblastoma (2); melanoma (2); metastatic disease (2); non-small cell lung carcinoma (2); prostate carcinoma (2); acute lymphoblastic leukemia (1); adenocarcinoma of the prostate (1); cervical cancer (1); colon cancer (1); infection (1); Lung (1); malignant mesothelioma (1); malignant pleural mesothelioma (1); multiple myeloma (1); Parkinson disease (1); renal carcinoma (1); retina degeneration (1); Retinal dystrophy (1); sarcoma (1); small cell lung carcinoma (1); squamous cell carcinoma (1); stomach cancer (1); thyroid cancer (1); uterine cancer (1).